JAK2 (Janus kinase 2)
Diseases named in the same sentence as JAK2 in open-access papers (continued):
Sharing a sentence is not in itself a finding about the gene and the disease.
cancer (continued). "Taken together, these data suggest that genome alterations due to lowered or loss of CHEK2 and JAK2 expression may exacerbate cancer progression and predict poor patient survival." (PMID 35851582, 2022). "MUC16 was shown to be associated with growth and metastasis of cancer cells through inhibition of the function of natural killer cells, the interaction with the janus kinase 2 (JAK2) leading to upregulation of the expression of the stem cell genes, and other molecular mechanisms." (PMID 35389164, 2022). "In the literature, the JAK2/STAT3 pathway was frequently associated with cancer metastasis." (PMID 31621555, 2020). "Thus, the current study aimed to elucidate the precise molecular mechanism underlying Nar anti-cancer function, especially regarding its influence on JAK2/STAT3 signaling pathway." (PMID 33680016, 2020). "A potential mechanism would be that mutations in JAK1/JAK2 might block PD-L1 induction, protecting cancer cells from immune attack." (PMID 30670049, 2019). "In line with our study, recent evidence has also implicated that the JAK2/STAT3 signaling pathway from a regulatory perspective due to its involvement in various fundamental biological processes as well as the pathogenesis of cancer." (PMID 30123088, 2018). "Taken together, this study demonstrated the clinical utility of targeted NGS with a focused hotspot cancer gene panel in NSCLCs and identified activating mutations in JAK2 and JAK3 with clinical implications inferred through integrative analysis of cancer genetic, genomic, and pharmacogenomic data." (PMID 29082853, 2017). "We found that the effects of pantoprazole on cancer cachexia-induced muscle wasting may be associated with the inhibition of inflammatory cytokines and/or the inactivation of the JAK2/STAT3 and ubiquitin proteasome pathways." (PMID 28489606, 2017). "Rather, it suggests that JAK2 deficiency by itself offers an advantage to certain cancer cells." (PMID 28977839, 2017). "However JAK2 copy number levels assessed in bulk TNBC biopsies by targeted resequencing of a panel of 196 cancer associated genes have been reported to be elevated in residual disease post neoadjuvant chemotherapy." (PMID 26317899, 2015). "In addition, serious questions were raised about the completeness and homogeneity of PV and other MPN cases reported to cancer registries, resulting in part from the recent addition of the JAK2 mutation to the diagnosis criteria." (PMID 20617023, 2010). "Compared to other cancers the hematopoietic neoplasms carry strikingly few mutations —in MPNs, almost half of all patients bear only a phenotypic driver mutation and genetic lesions in younger patients below the age of 39 appear to be confined to the phenotypic driver mutations JAK2, CALR, or MPL." (PMID 32731609, 2020). "Inhibition of key pro-survival signaling pathways such as PI3K/AKT/mTOR and JAK2/STAT3 is significant for systematically dismantling the defense mechanisms of cancer cells, exhibiting extensive cross-talk with mechanisms discussed in other sections." (PMID 41599293, 2026). "Macrophage-derived IL-6 subsequently activates the JAK2/STAT3 pathway in cancer cells, suppressing ENZ-induced apoptosis and conferring therapeutic resistance." (PMID 41990247, 2026). "JAK2/STAT3 is a classical inflammatory pathway that plays an important role in regulating the transition from inflammation to cancer." (PMID 41200213, 2025). "The JAK2/STAT3 signaling pathway, a member of the STAT family of transcription factors, is closely associated with the onset of various cancers and regulates cancer cell proliferation and migration." (PMID 40723784, 2025). "Recent studies have shown that most members of the USP family are involved in regulating the aberrant activation of the JAK2/STAT3 signaling pathway in malignant tumors." (PMID 40936898, 2025).
cancer (continued). "To uncover innovative targeted therapeutic approaches in this disease subtype we performed genome-scale CRISPR-Cas9 screening that highlighted a strong, selective dependency on JAK2 compared to other types of cancer." (PMID 40470252, 2025). "These inhibitors work by blocking the JAK2 kinase activity, preventing the activation of downstream signaling pathways that promote cancer cell growth." (PMID 40486651, 2025). "In colorectal cancer tissues, B7-H3 induces cancer cell migration and invasion through the Jak2/Stat3/MMP-9 signaling pathway." (PMID 40519928, 2025). "This study complemented these findings by demonstrating that in CRC, Prkci specifically activated the Jak2/Stat3 pathway, which was known for its involvement in cancer cell survival, proliferation, and angiogenesis." (PMID 40840329, 2025). "(ii) Various investigations have demonstrated that B7-H3 regulates cancer progression through multiple signaling pathways including, JAK2/STAT3, NF-Κb, PI3K/AKT, and ERK." (PMID 41440959, 2025). "Cell cycle regulation is tightly linked to several key signaling pathways, including the JAK2/STAT3 pathway, which has been identified as a critical regulator of cell cycle progression and proliferation in many cancers." (PMID 40075566, 2025). "In breast cancer, the JAK2/STAT3 axis is involved in the B7-H3-mediated reduction in cancer cell sensitivity to Paclitaxel." (PMID 40214484, 2025). "Both Src and JAK2 are tyrosine kinases, and JAK2 not only plays an important role in cancer cell apoptosis and metastasis but is activated by PTPRO deletion." (PMID 40016288, 2025). "Previous studies had not reported this specific phosphorylation site in the context of Jak2′s role in angiogenesis, making our findings a significant contribution to the understanding of Jak2 regulation in cancer." (PMID 40840329, 2025). "Constitutively active JAK2 has been observed in various cancer types, including breast cancer, lymphomas, and myeloid malignancies." (PMID 40332385, 2025). "Current research indicates that the JAK2/STAT3 pathway plays a crucial role in promoting cancer cell growth, invasion, metastasis, and anti-apoptosis, particularly in triple-negative breast cancer, melanoma, and other tumor diseases." (PMID 39940837, 2025). "In terms of adjuvant therapy, KLT increases cancer cell sensitivity to chemotherapeutics via JAK2/STAT3 and NF-κB pathway modulation, downregulating MDR1, MRP1, and PVT1, while mitigating chemotherapy-related adverse effects." (PMID 41164166, 2025). "In lung cancer, IL-6 mediates interactions between cancer cells and microglia via Jak2/STAT3 signaling, aiding brain metastasis, a significant mortality driver." (PMID 39286635, 2024). "Interleukin-6 (IL-6), a pro-inflammatory cytokine, facilitates cancer development by activating the Janus kinase 2 (JAK2)–signal transducer and activator of transcription 3 (STAT3) pathways." (PMID 38672257, 2024). "In this study, we sought to define the relationships between JAK2 mutation and the response to ICI therapy and immunogenic profile of cancers." (PMID 38200372, 2024). "The JAK2/STAT3 signaling pathway is implicated in various physiological and pathological processes, including cancer, inflammation, and tissue injury." (PMID 38787114, 2024). "Lycorine and lycorine hydrochloride induced apoptosis in cancer cells by regulating multiple intracellular pathways including NF-κB, JAK2/STAT3, and JNK pathways, which are crucial for cancer cell survival and growth." (PMID 39245716, 2024). "The JAK2/STAT3 signaling pathway is crucial in cancer development, involved in processes like immune regulation, angiogenesis, cell proliferation, and differentiation." (PMID 39781272, 2024). "The activation of the Jak2/Stat3 signaling pathway is a key factor in the occurrence of various malignant tumors." (PMID 39203920, 2024).
cancer (continued). "The present study has identified 4 cancer driver genes (PTCH1, DNMT3A, PTPRS, JAK2) that rank highest in responders and are linked to enhanced survival in the validation cohort, either as individual markers or as part of a grouped marker panel." (PMID 38951894, 2024). "Since cucurbitacin I exhibits an antitumor effect, cucurbitacin I and JAK2/STAT3 inhibitors have received increasing attention as potential cancer therapeutic agents." (PMID 39255287, 2024). "In cancer autophagy, the interaction of Beclin-1 with JAK2 is triggered by IL-6, which allows JAK2 to phosphorylate Beclin-1 at the Y333 site." (PMID 38887520, 2024). "We observed that NP suppressed the levels of Jak2/Stat3, which regulates the growth and proliferation of cancer cells, but further studies are needed to determine the intracellular mechanisms through which it exerts this effect." (PMID 39459502, 2024). "JAK2/STAT3 signaling has been widely implicated in mitochondria-dependent apoptosis and cancer metastasis, thus attracted our attentions and western blotting was applied to compare JAK2/STAT3 pathway activity in PTPRO-overexpressing and control groups." (PMID 38182570, 2024). "Research has elucidated that the JAK2/STAT3/Cyclin D2 signaling pathway is pivotal in promoting cancer stem cell proliferation." (PMID 38699644, 2024). "Up to now, to our knowledge, research on the influence of JAK2 on cell proliferation has mainly focused on human cancer cells." (PMID 38612844, 2024). "The phosphorylation of JAK1, JAK2, and c-Src in diverse cancer cell lines was also suppressed by various terpenoids." (PMID 38397437, 2024). "Ginsenosides induce apoptosis and cell cycle arrest, suppress the proliferation of cancer cells, induce senescence markers, and suppress the leukemia cancer cells via different signaling pathways including the JAK2/STAT5 signaling pathway." (PMID 38706463, 2024). "Overall, the role of the JAK2 gene in cancer treatment highlights its potential as a target, while its relevance to older cancer patients requires further investigation." (PMID 38590525, 2024). "Recently, numerous studies have indicated that overly activated JAK/STAT signaling promotes the proliferation, migration, and invasion of cancer cells in CC, whereas the inhibition of JAK2/STAT3 signaling suppresses cancer progression." (PMID 38673975, 2024). "Specifically, in TNBC, studies have demonstrated that downregulating the JAK2/STAT3 pathway can significantly inhibit cancer stem cell proliferation." (PMID 38699644, 2024). "HCC cell‐secreted exosomal PSMA5 knockdown hinders M2 polarization to suppress cancer progression by restraining JAK2/STAT3 signaling." (PMID 38415977, 2024). "This interventional strategy was experimentally demonstrated in an immunocompetent mouse model of cancer using L19-mIL12 and Ruxolitinib, a commercially available JAK2 inhibitor." (PMID 38448543, 2024). "This suggests that it is possible that anlotinib exerts its inhibitory effect on cancer cell development by inhibiting the Jak-2/Stat3 signaling axis." (PMID 39193386, 2024). "The STAT5, STAT3, and JAK2 signaling pathways play an important role in inhibiting the growth and differentiation of cancer cells." (PMID 39063337, 2024). "The JAK2/STAT3 signalling pathway is closely associated with the occurrence and development of many diseases, particularly cancer." (PMID 38879667, 2024). "TAMs are an important source of IL-6, which regulates the expression of m6A regulators and activates the JAK2/p-STAT3 pathway in cancer cells." (PMID 38872221, 2024). "Our results unveiled the molecular mechanisms of metochalcone against carcinomas, which are dependent on the JAK2/STAT3 signaling axis to induce SASP." (PMID 38686052, 2024). "Chalcones have emerged as potential molecular therapeutics against malignant carcinomas via modulation JAK2/STAT3 signaling pathway." (PMID 38686052, 2024).
cancer (continued). "It has been suggested that frequent chromosomal losses of JAK2 is a result of co-deletion with the tumour suppressor gene CDKN2A on chromosome arm 9p across cancer types." (PMID 37837931, 2023). "TG-101348 is an ATP-competitive Janus kinase 2 (JAK2) inhibitor with antitumor activity by inducing cancer cell apoptosis." (PMID 36845395, 2023). "The JAK2/STAT3 signaling pathway is a crucial target among the three ATLs pathways for cancer therapy." (PMID 37241729, 2023). "JSI-124 has been identified as a selective inhibitor of the JAK2/STAT3 signaling pathway in various types of cancer." (PMID 38001999, 2023). "Collectively, these findings nominate JAK2 inhibitors as potential drugs for the treatment of KRAS-driven cancers." (PMID 37210549, 2023). "AG490 is a selective inhibitor of JAK2 that inhibits the phosphorylation of STAT3 in various cells including cancer cells." (PMID 37846594, 2023). "Both the survival and expansion of many types of cancer cells depend on the JAK2/STAT3 signaling pathway." (PMID 36852795, 2023). "Continuous activation of JAK2/STAT3 signaling pathway is often associated with the proliferation, invasion, metastasis and other behaviors of malignant tumors, which is also the focus of research on JAK/STAT signaling pathway." (PMID 37575547, 2023). "Hyperactivation of JAK 2 promotes tumorigenesis, the over proliferation of tumors, and the overall survival of cancer cells." (PMID 38127921, 2023). "This suggests that the reovirus treatment was in effect around D8, preventing JAK2 from being downregulated, as was seen in other types of proliferating human cancers." (PMID 37873786, 2023). "Recent investigations have demonstrated that the anti-cancer activity of the three atractylenolides can be attributed to their influence on the JAK2/STAT3 signaling pathway." (PMID 37241729, 2023). "In light of this challenge, our investigation into the interaction of PRMT6 with JAK2 to activate the STAT3 pathway led us to consider PRMT6 inhibitors as a potentially effective approach for cancer treatment." (PMID 37813837, 2023). "Alternatively, data have revealed that inhibition of the JAK2/STAT3 signaling pathway results in the downregulation of CSC markers in cancers, which weakens the stemness characteristics of CSCs." (PMID 37853437, 2023). "Multiple oncogenic signaling cascades (EGFR, CXCR4, FASN, P-gp, β-catenin, GSK-3B, STAT1, JAK2, MUC1, etc) are hallmarks of cancer cells that are associated with drug resistance, tumorigenic potential, and metastasis." (PMID 37151801, 2023). "Leptin is known to activate a variety of signalling pathways, in particular the JAK2/STAT3 pathway included in these cancer cells." (PMID 37238197, 2023). "To investigate this, we probed the interaction between STAT3 and JAK2 in cancer cells expressing either Vector or PRMT6." (PMID 37813837, 2023). "It has been previously documented that PLA2R1 can inhibit cancer progression by activating the Janus kinase 2 (JAK2) pathway and inducing estrogen-related receptor alpha (ESRRA)." (PMID 37345058, 2023). "It has been evidenced that the inhibition of the JAK2/STAT3 pathway potentiates apoptosis in cancer cells." (PMID 37009004, 2023). "Of these genes, GNAQ, GNAS, and JAK2 are associated with cell growth-related factors, whereas NRAS, IDH2, and CTNNB1 are cancer-related genes." (PMID 36780540, 2023). "Previous studies have shown that CAFs promote carcinoma progression by inducing EMT via the IL-6/JAK2/STAT3 pathway or paracrine TGF-β." (PMID 37254126, 2023). "The JAK2/STAT3 pathway plays an important role in cell growth, proliferation and survival and has been associated with many human cancers 22-24." (PMID 35517401, 2022). "Previously, co-treatment with Janus kinase 2 (JAK2) inhibitors sensitized P-gp-overexpressing drug-resistant cancer cells." (PMID 35562984, 2022).
cancer (continued). "Among the commercially available JAK2 inhibitors, three demonstrated cytotoxic effects in P-gp-overexpressing resistant cancer as part of combination therapies, including CEP-33779, NVP-BSK805, and XL019." (PMID 35562984, 2022). "LDOC1 deficiency leads to enhanced IL-6/JAK2/STAT3 loop, through which LDOC1 mediates cancer progression." (PMID 36591515, 2022). "Though, IPF shares a series of risk factors (ageing, smoking and environmental exposures), pathogenic pathways (PI3K-γ/AKT, JAK2/STAT3) and biological abnormalities (genetic and epigenetic alterations) with cancer." (PMID 35626663, 2022). "Collectively, these results indicate that JAK2-mediated phosphorylation of STIP-1 is critical for sustaining the JAK2/STAT3 signaling pathway in cancer cells." (PMID 35269562, 2022). "Many studies have reported that the activation of JAK2/STAT3 pathway contributes to the progression of various cancers." (PMID 35418176, 2022). "Mutations in JAK2, which lead to the hyperactivation of the JAK/STAT pathway, have been observed in many cancer types." (PMID 35954343, 2022). "The activation of JAK2 and the resulting dimerization of P-STAT3 regulate gene expressions, such as Bcl2, cyclinD, survivin, and XIAP, which causes cancer cell proliferation and resistance to anticancer drugs." (PMID 36500220, 2022). "Signal transducer and activator of transcription 3 (STAT3) phosphorylation in the cancer cells cultured on polymer X was upregulated by the fibronectin-integrin α5-Janus kinase 2 (JAK2) axis and maintained by the cytosolic LMO2/LBD1 complex." (PMID 36359204, 2022). "IL-6/JAK2/STAT3 pathway are more active in breast CSCs compared with other cancer cells, and thereby, number of CSCs as well as growth of xenograft are decreased following JAK2 inhibition." (PMID 35505363, 2022). "IL-17 can also promote cancer-cell proliferation by activating the Janus kinase 2/signal transducers and activators of the transcription (JAK2/STAT3) pathway." (PMID 36230676, 2022). "Our study provides a basis for the development of JAK2 inhibitor-based therapies for drug-resistant cancers." (PMID 35562984, 2022). "Concordantly, analysis of clinical cancer datasets revealed that deletion of JAK2 is associated with increased genome alteration; and alteration in CHEK2 and JAK2 is linked to preferential deletion or amplification of cancer-related genes." (PMID 35851582, 2022). "Activation of the JAK2/STAT3 pathway can promote cell survival and proliferation, inhibit apoptosis, and is implicated in the occurrence and development of various cancers." (PMID 35116094, 2022). "This is, to our knowledge, the first study to demonstrate that tyrosine phosphorylation of STIP1, mediated by JAK2, can affect a number of biological functions in cancer cells." (PMID 35269562, 2022). "SOCS2 was identified as a key direct target gene of miR-877-3p in GC, where miR-877-3p suppressed the expression of SOCS2 and promoted cancer cell stemness and chemoresistance subsequently by activating Jak2/Stat3 signaling." (PMID 35600882, 2022). "Mutations involved in the amino acid residue R683 of JAK2 are commonly found in childhood cancers and impact the auto-regulation of JAK2 activity." (PMID 36497424, 2022). "A dysfunctional JAK2/STAT3 signaling pathway can induce cancer and inhibit apoptosis, promote cancer cell migration by regulating E-cadherin and vimentin expression, and promote EMT." (PMID 36158694, 2022). "Here, we further examined the reciprocal interactions between STIP1 and JAK2 with the goal of advancing our understanding of their functional role in cancer cells." (PMID 35269562, 2022). "The epigenetic mechanisms associated with quercetin are the suppression of Janus kinase 2 (JAK2) with the inhibition of the proliferation, invasion, and migration of cancer cells." (PMID 36235389, 2022). "JAK2 and CALR mutations generate cancer-specific neoantigens that are recognized by effector T cells." (PMID 35603202, 2022).